ATG10 (autophagy related 10)
Description:
E2-like enzyme involved in autophagy. Acts as an E2-like enzyme that catalyzes the conjugation of ATG12 to ATG5. ATG12 conjugation to ATG5 is required for autophagy. Likely serves as an ATG5-recognition molecule. Not involved in ATG12 conjugation to ATG3 (By similarity). Plays a role in adenovirus-mediated cell lysis.
Synonyms: APG10L; PP12616; DKFZP586I0418; FLJ13954; APG10; ATG10S
Tractability: PROTAC: ubiquitination databases record sites on it.
Gene: Protein-coding gene on chromosome 5 (81,971,615 to 82,276,857, forward strand). Ensembl gene ENSG00000152348.
Subcellular location: Cytoplasm
Subcellular location (Human Protein Atlas): Nucleoli; Nucleoplasm
Pathways (Reactome):
Autophagy: Macroautophagy
Gene Ontology:
Molecular function: Atg12 conjugating enzyme activity; protein binding; Atg12 transferase activity; ubiquitin-like protein transferase activity
Biological process: autophagosome assembly; autophagy; ER overload response; protein modification by small protein conjugation; mitophagy
Cellular component: cytosol; cytoplasm
Genetic constraint (gnomAD): Loss-of-function variants: 9 observed, 8.53 expected, observed/expected ratio (o/e) 1.06, 90% interval 0.63 to 1.74. That is too few expected variants to judge how well the gene tolerates losing a copy. Missense variants: 69 observed, 86.48 expected, observed/expected ratio (o/e) 0.8, 90% interval 0.66 to 0.98. Synonymous variants: 29 observed, 32.43 expected, observed/expected ratio (o/e) 0.89, 90% interval 0.67 to 1.22.
Homologues: Orthologues: chimpanzee ATG10 (99% identical), pig ATG10 (82% identical), mouse Atg10 (79% identical), guinea pig ATG10 (76% identical), dog ATG10 (72% identical), rat Atg10 (70% identical), macaque ATG10 (70% identical), zebrafish atg10 (46% identical).
Diseases named in the same sentence as ATG10 in open-access papers:
ATG10 is named in the same sentence as 63 diseases in open-access papers, as found by Europe PMC text mining. Sharing a sentence is not in itself a finding about the gene and the disease. The quoted sentences say what the papers report.
colorectal cancer (21 papers, 2012 to 2025). A primary or metastatic malignant neoplasm that affects the colon or rectum. "ATG10 overexpression has been associated with poor prognosis and adverse clinicopathological features in gastric cancer, colorectal cancer and acute leukemia, as determined by RT-PCR, immunohistochemistry and western blotting." (PMID 40313244, 2025). "The overexpression of ATG10 is also associated with lymphatic invasion and lymph node metastasis in colorectal cancer." (PMID 34631695, 2021). "In colorectal cancer, increased ATG10 expression is associated with lymph node metastasis and lymphovascular invasion." (PMID 33095808, 2020). "Our findings show that increased ATG10 expression is strongly associated with lymph node metastasis and lymphovascular invasion in colorectal cancer." (PMID 23285162, 2012). "Consistent with these previous studies, our results showed that ATG10 expression is closely associated with lymphovascular invasion and lymph node metastasis in colorectal cancer." (PMID 23285162, 2012). "Similarly, in colorectal cancer, ATG10 overexpression is linked to poorer overall and disease-specific survival, as well as increased lymphovascular invasion and lymph node metastasis." (PMID 40313244, 2025). "Moreover, ATG10 modulated epithelial mesenchymal-associated protein depletion in colorectal cancer cells." (PMID 36598250, 2023). "Increased expression of ATG10 in colorectal cancer is also associated with invasion and metastasis." (PMID 33704908, 2021). "In conclusion, ATG10 up-regulation in colorectal cancer is closely associated with lymphovascular invasion and lymph node metastasis, indicating that ATG10 may be useful as a prognostic marker and as a therapeutic target in colorectal cancer." (PMID 23285162, 2012). "ATG10 is abnormally overexpressed in multiple cancers, including gastric cancer, colorectal cancer and acute leukemia, and its overexpression is strongly associated with poor prognosis and adverse clinicopathological features." (PMID 40313244, 2025). "ATG10 expression is significantly elevated in endometrial cancer, hepatocellular carcinoma, acute leukemia, nasopharyngeal carcinoma, gastric cancer and colorectal cancer compared to normal tissues." (PMID 40313244, 2025). "The c-Myc/miR-27b-3p/ATG10 signaling pathway was involved in regulating colorectal cancer chemoresistance." (PMID 36598250, 2023). "In vitro and in vivo studies showed the miR-27b capacity to sensitize colorectal cancer cells to oxaliplatin by acting on c-Myc/ATG10 chemoresistance signaling pathway." (PMID 36501111, 2022). "ATG10 expression is considered to be closely related to lymphatic infiltration and lymph node metastasis of colorectal cancer, and lymphatic infiltration and lymph node metastasis can affect the overall survival of patients." (PMID 34636718, 2021). "A recent study has demonstrated that miR‐27b‐3p regulates the expression of ATG10 at the posttranscriptionally level in colorectal cancer cells in vitro and in vivo." (PMID 33904657, 2021). "ATG10 is an autophagic E2-like enzyme which has been found to be overexpressed in colorectal cancer and lung cancer." (PMID 34631695, 2021). "ATG10 has been explored in a variety of tumors, including colorectal cancer, gastric cancer, non-small-cell lung cancer, and breast cancer." (PMID 34746309, 2021). "Specifically, we found that in oxaliplatin-resistant colorectal cancer cells, the increased chemoresistance and autophagy are due to the enhanced expression of c-Myc, which upregulates the expression of ATG10 by suppressing miR-27b-3p." (PMID 32104496, 2020). "Another study reported that ATG10, one of the E2-like conjugation enzymes for ATG12-ATG5 conjugation, was highly increased in colorectal cancer tissues, and increased protein expression was associated with lymphovascular invasion and lymph node metastasis." (PMID 24723943, 2014).
colorectal cancer (continued). "Protein expression analysis showed that ATG10 is highly increased in colorectal cancer (tissue - 18/37 cases, 48%; cell line –8/12 cell lines, 66%)." (PMID 23285162, 2012). "To evaluate ATG10 expression in colorectal cancer, we first analyzed colorectal cancer tissues by Western blot." (PMID 23285162, 2012). "Unlike ATG6, which is down-regulated in cancer, the present results indicate that ATG10 is increased in colorectal cancer." (PMID 23285162, 2012). "To investigate the clinicopathological role of ATG10 in colorectal cancer, we analyzed ATG10 expression in colorectal cancer tissues and cell lines." (PMID 23285162, 2012). "Notably, ATG10 overexpression also induces resistance to oxaliplatin in colorectal cancer (SW480) cells." (PMID 40313244, 2025). "ATG10, a member of the ATG family, has been implicated in various malignancies, including endometrial cancer, hepatocellular carcinoma, acute leukemia, nasopharyngeal carcinoma, gastric cancer and colorectal cancer." (PMID 40313244, 2025). "Furthermore, PTPB1 directly interacts with ATG10 mRNA and negatively regulates its expression, promoting tumor metastasis in colorectal cancer cells." (PMID 39715205, 2024). "PTBP1 also contributes to colorectal cancer cells metastasis through downregulation of ATG10." (PMID 36949664, 2023). "The C-myc/miR-27b-3p/ATG10 regulatory axis regulates chemoresistance in colorectal cancer." (PMID 35211403, 2022). "Furthermore, western blot showed that ATG10 was the most significantly upregulated protein in oxaliplatin-resistant colorectal cancer cells." (PMID 32104496, 2020). "Next, we investigated the effect of ATG10 on autophagic activity in colorectal cancer cells." (PMID 32104496, 2020). "Increased expression of ATG10 in colorectal cancer is associated with lymphovascular invasion and lymph node metastasis indicating that ATG10 may be a potential prognostic maker in colorectal cancer." (PMID 23285162, 2012). "Taken together, these results indicate that ATG10 is up-regulated in colorectal cancer." (PMID 23285162, 2012). "ATG10 was increased in 18 of the 37 cases (48%) of colorectal cancer." (PMID 23285162, 2012). "In this study, we evaluated ATG10 expression in patients with sporadic colorectal cancer." (PMID 23285162, 2012). "Moreover, the c-Myc/miR-27b-3p/ATG10 axis regulates chemoresistance in colorectal cancer." (PMID 33897436, 2021). "Furthermore, we observed that the c-Myc/miR-27b-3p/ATG10 regulatory axis could upregulate autophagy, leading to chemoresistance in colorectal cancer." (PMID 32104496, 2020). "Similarly, colorectal cancer cell lines (HCT116, HT29, KM12C, WiDr, LoVo, SW480, SW48, HCT15, DLD1, RKO and CaCo2) exhibit significantly higher ATG10 expression than CCD841 cells." (PMID 40313244, 2025).
breast cancer (18 papers, 2012 to 2026). A primary or metastatic malignant neoplasm involving the breast. "It’s reported that potentially functional polymorphisms in ATG10 were found to be associated with risk of breast cancer and acute myeloid leukemia." (PMID 35902797, 2022). "This SNP was located in the second intron of the ATG10 gene and had been reported to have a significant association with susceptibility for breast cancer and many other diseases in Chinese populations." (PMID 34359652, 2021). "The rs10514231 is located in the second intron of ATG10 and has been reported for association with breast cancer risk (C allele: OR = 0.75, 95%CI: 0.59–0.93, p = 0.010)." (PMID 34359652, 2021). "The strongest statistical evidence of interaction was found in relation to ER– breast cancer risk and was noted between an intron variant 5q14‐rs7707921 in the autophagy related 10 (ATG10) gene, and alcohol consumption (pint =1.9 × 10−5)." (PMID 28670784, 2017). "Importantly, both rs1864182 and rs1051423, located in ATG10, have been reported to be associated with a decreased risk of breast cancer." (PMID 27748080, 2016). "It was located in the second intron of ATG10 and showed gene regulatory activity in most breast cancer cells we used." (PMID 34359652, 2021). "The chromosomal region of ATG10 (5q14) is frequently lost in ovarian cancer, gastric cancer, and breast cancer." (PMID 23285162, 2012). "Five of these were strong cross-tissue eQTLs in GTEx (for ATG10, ATP6AP1L, and RPS23, all associated with rs7707921, and C5orf35 (also known as SETD9) and rs889312; P < 1 × 10− 5 in at least 19 tissues with concordant directionality) and maintain their regulatory capacity in breast cancer cells." (PMID 30205839, 2018). "In a 2021 study, exosomal lncRNA AGAP2-AS1 was able to modulate autophagy through Autophagy related 10 (ATG10), which made breast cancer cells resistant to trastuzumab." (PMID 39925739, 2025). "ATG10 (autophagy-related 10) expression induces autophagy, leading to lncRNA AGAP2-AS1 mediated trastuzumab resistance in breast cancer, the expression of ectopic ATG10 is significantly related to lymph node metastasis and poorer prognosis in this cancer." (PMID 35813295, 2022). "According to the literature, all 3 identified LNM-upregulated genes, i.e. ATG10, GATA3 and S100B, are considered markers of breast cancer cells and their invasive potential." (PMID 33658651, 2021). "Cumulative evidence has reported that autophagy plays an essential role in breast cancer, which involved many ATGs (autophagy-related genes), such as BECN1, ULK1, ATG5, and ATG10, or autophagy signaling pathways, such as AMPK/mTOR." (PMID 34359652, 2021).
lung carcinoma (12 papers, 2017 to 2025). "Autophagy, a key cellular process, is tightly linked to cancer development; genes like ATG5 and ATG10 influence lung cancer progression, and epigenetic regulators modulate autophagy-related carcinogenesis." (PMID 40832611, 2025). "For example, low ATG5 expression reduces cell growth in RAS mutant lung cancer cell lines.ATG10 overexpression was associated with poor prognosis in lung cancer." (PMID 40832611, 2025). "High expression of Atg10 is associated with poor prognosis for lung cancer, and autophagy gene Atg7 knockout leads to the progression of lung cancer to eosinophilic cell tumors, inhibiting tumor proliferation." (PMID 33194668, 2020). "The same study further denoted that the enhanced expression of ATG10 might associate with shortened survival time in lung cancer." (PMID 34461934, 2021). "High expression levels of ATG10 were associated with an unfavorable prognosis in lung cancer." (PMID 31811814, 2019). "Moreover, high expression levels of autophagy-related gene 10 (ATG10) were associated with an unfavorable prognosis in lung cancer." (PMID 31811814, 2019). "Functional analyses of ATG10 rs10036653 polymorphism suggested that ATG10 A allele might increase transcription factor OCT4 binding affinity compared to the T allele in lung cancer cells." (PMID 29259263, 2017). "ATG10, an autophagy-related protein, boosted lung cancer cell proliferation and migration." (PMID 34461934, 2021). "Mounting evidence has shown that ATG10 had increased level of expression in malignancies such as CRC and lung cancer." (PMID 33904657, 2021). "Emerging evidence has emphasized that ATG10 displayed higher expression level in tumors of malignancies such as CRC 41 and lung cancer." (PMID 32104496, 2020).
gastric cancer (11 papers, 2012 to 2025). A primary or metastatic malignant neoplasm involving the stomach. "In gastric cancer, low expression of ATG10 and ATG3 were associated with lymph node metastasis and advanced TNM stage; both ATG10 and ATG3 were found to be favorable independent prognostic factors for overall survival." (PMID 28696368, 2017). "In vivo experiments confirm that ATG10 overexpression increases tumorigenicity in gastric cancer (SGC-7901) and nasopharyngeal carcinoma (CNE-2) cells in nude mice." (PMID 40313244, 2025). "In gastric cancer, elevated ATG10 expression correlates with reduced overall survival, lymph node metastasis and advanced TNM staging." (PMID 40313244, 2025). "ATG10 is highly expressed in gastric cancer (GC) and may act as an oncogene to regulate the cell cycle and promote abnormal cell proliferation." (PMID 36147481, 2022). "However, in gastric cancer, the low expression of ATG10 affects its lymph node metastasis." (PMID 34636718, 2021).
lymph node metastasis (7 papers, 2012 to 2025). "The results showed that ATG10 expression was highly associated with lymphovascular invasion (P<0.001) and lymph node metastasis (P = 0.005)." (PMID 23285162, 2012). "In a multivariate analyses with potential survival variables, lymph node metastasis alone was significantly associated with survival parameters, whereas ATG10 expression was not (Hazard Ratio, 4.736 vs. 1.404; 95% Confidence Interval, 1.763–12.723 vs. 0.676–2.916; P = 0.002 vs. 0.363)." (PMID 23285162, 2012).
hepatocellular carcinoma (4 papers, 2018 to 2025). A malignant tumor that arises from hepatocytes. "In hepatocellular carcinoma, ATG10 levels are markedly higher in Hep3B, HepG2 and PLC cell lines compared to normal LO2 cells." (PMID 40313244, 2025). "Downregulation of ATG10 suppresses hepatocellular carcinoma cell proliferation, migration and invasion by modulating cyclin B1, CDK1 and CDK2 expression." (PMID 40313244, 2025). "In prediction models for autophagy-related genes, multiple autophagy genes are involved, such as ATG10, ATIC, BIRC5, and CAPN10, and their changes effectively affect the survival time of hepatocellular carcinoma patients." (PMID 39502521, 2024).
nasopharyngeal carcinoma (4 papers, 2022 to 2025). A carcinoma arising from the nasopharyngeal epithelium. "In nasopharyngeal carcinoma and ovarian cancer, ATG10 inhibition disrupts the PI3K/AKT signaling pathway and epithelial-mesenchymal transition, respectively." (PMID 40313244, 2025). "ZFAS1 regulates the expression of ATG10 by competitively adsorbing miR-100-3p to promote the proliferation and metastasis of nasopharyngeal carcinoma cells in vivo and in vitro." (PMID 34980191, 2022). "In nasopharyngeal carcinoma (NPC), the lncRNA ZFAS1, whose RNA stability is enhanced by the m6A methyltransferase METTL3, promotes NPC cell proliferation, migration and tumor growth and regulates autophagy levels by modulating the miR-100-3p/ATG10 axis and through the PI3K/AKT pathway." (PMID 38933333, 2024).
Parkinson disease (4 papers, 2018 to 2023). A progressive degenerative disorder of the central nervous system characterized by loss of dopamine producing neurons in the substantia nigra and the presence of Lewy bodies in the substantia nigra and locus coeruleus. "It has been associated with the promotion of neuronal damage in Parkinson’s disease (MPP+-triggered neuronal damage in SK-N-SH cells) via the miR-874-5p/ATG10 axis." (PMID 34830203, 2021). "In the substantia nigra of a Parkinson’s disease (PD) rat model, p62, Atg5, Atg12, LC3, and Atg16l1 were expressed, while Atg10 was not expressed." (PMID 36598250, 2023).
melanoma (3 papers, 2016 to 2017). A malignant, usually aggressive tumor composed of atypical, neoplastic melanocytes. "We examined five single‐nucleotide polymorphisms (SNPs) in three ATG genes (ATG5;ATG10; and ATG16L) with known or suspected impact on autophagic flux in an international population‐based case–control study of melanoma." (PMID 27748080, 2016). "However, GAA and ATG10 protein levels were found to be increased, following SIRT6 knockdown in melanoma cells." (PMID 29234488, 2017).
colon cancer (2 papers, 2013 to 2021). "ATG10 promotes the proliferation and migration of lung and colon cancer cells." (PMID 34631695, 2021). "Notably, knockdown of ATG10 in Sox2-expressing colon cancer cells restored cancer cell properties." (PMID 23451179, 2013).
colorectal tumors (2 papers, 2018 to 2020). "In addition, the expression of ATG10 was decreased after overexpression of miR-27b-3p and increased after inhibition of miR-27b-3p in the subcutaneous colorectal tumors." (PMID 32104496, 2020).
endometrioid adenocarcinoma (2 papers, 2020 to 2021). An adenocarcinoma characterized by the presence of malignant glandular epithelial cells resembling endometrial cells. "ATG10 is a target gene of miR-369-3p, which inhibits cell proliferation and migration by targeting cancer cells via autophagy in endometrioid adenocarcinoma." (PMID 33095808, 2020).
glioma (2 papers, 2019 to 2023). A benign or malignant brain and spinal cord tumor that arises from glial cells (astrocytes, oligodendrocytes, ependymal cells). "For example, autophagy-related genes, including ULK1, ATG10, and ATG16L2, possess a prognostic value in glioma cohorts and were used as the biomarkers in diagnosing glioma." (PMID 37182147, 2023).
head and neck squamous cell carcinoma (2 papers, 2014 to 2017). A squamous cell carcinoma that arises from any of the following anatomic sites: lip and oral cavity, nasal cavity, paranasal sinuses, pharynx, larynx, and salivary glands. "MiR-630 was also found to be upregulated in head and neck squamous cell carcinoma after cisplatin treatment and can modulate the protein expression of ATG5, ATG6/BECN1, ATG10, ATG12, ATG16L1 and UVRAG." (PMID 24621930, 2014).
laryngeal carcinoma (2 papers, 2017). Carcinoma that arises from the laryngeal epithelium. "Analysis of laryngeal cancer showed an association between the less common allele genotypes (CT + TT) in ATG10 rs1864183 and a higher risk to develop it." (PMID 28761177, 2017). "We found an association between the variant in ATG10 rs1864183 and a higher susceptibility to develop laryngeal cancer, ATG2B rs3759601 and pharyngeal cancer and ATG16L1 rs2241880 and oral carcinoma." (PMID 28761177, 2017).